CXCL9 (C-X-C motif chemokine ligand 9)
Description:
Cytokine that affects the growth, movement, or activation state of cells that participate in immune and inflammatory response. Chemotactic for activated T-cells. Binds to CXCR3.
Synonyms: HuMIG; MIG; CMK; SCYB9; crg-10
Tractability: Antibody: its Gene Ontology location is reachable by antibodies, with high confidence; UniProt places it where antibodies can reach, with medium confidence; UniProt predicts a signal peptide or a membrane-spanning region. PROTAC: ubiquitination databases record sites on it.
Gene: Protein-coding gene on chromosome 4 (76,001,275 to 76,007,509, reverse strand). Ensembl gene ENSG00000138755.
Subcellular location: Secreted
Pathways (Reactome):
Signal Transduction: Chemokine receptors bind chemokines; G alpha (i) signalling events
Gene Ontology:
Molecular function: chemokine activity; CXCR3 chemokine receptor binding; protein binding; CXCR chemokine receptor binding; cytokine activity
Biological process: adenylate cyclase-activating G protein-coupled receptor signaling pathway; chemotaxis; positive regulation of release of sequestered calcium ion into cytosol; regulation of cell population proliferation; cell-cell signaling; cellular defense response; cellular response to lipopolysaccharide; chemokine-mediated signaling pathway; defense response; G protein-coupled receptor signaling pathway; inflammatory response; neutrophil chemotaxis; signal transduction; immune response
Cellular component: extracellular region; external side of plasma membrane
Genetic constraint (gnomAD): Loss-of-function variants: 6 observed, 8.67 expected, observed/expected ratio (o/e) 0.69, 90% interval 0.38 to 1.36. That is too few expected variants to judge how well the gene tolerates losing a copy. Missense variants: 73 observed, 83.72 expected, observed/expected ratio (o/e) 0.87, 90% interval 0.72 to 1.06. Synonymous variants: 28 observed, 30.52 expected, observed/expected ratio (o/e) 0.92, 90% interval 0.68 to 1.26.
Homologues: Orthologues: chimpanzee CXCL9 (100% identical), macaque CXCL9 (92% identical), pig CXCL9 (76% identical), rabbit CXCL9 (71% identical), mouse Cxcl9 (69% identical), guinea pig CXCL9 (66% identical), rat Cxcl9 (65% identical), zebrafish cxcl11.6 (30% identical), zebrafish cxcl11.7 (30% identical), zebrafish cxcl11.3 (29% identical), zebrafish cxcl11.5 (24% identical), zebrafish cxcl11.8 (23% identical), and 1 more. Paralogues in human: CXCL2 (32% identical), CXCL3 (30% identical), CXCL1 (30% identical), CXCL10 (30% identical), CXCL5 (26% identical), CXCL11 (26% identical), CXCL6 (25% identical), PPBP (23% identical), CXCL8 (22% identical), PF4 (21% identical), CXCL13 (20% identical), PF4V1 (19% identical).
Diseases named in the same sentence as CXCL9 in open-access papers:
CXCL9 is named in the same sentence as 513 diseases in open-access papers, as found by Europe PMC text mining. Sharing a sentence is not in itself a finding about the gene and the disease. The quoted sentences say what the papers report.
melanoma (179 papers, 2007 to 2026). A malignant, usually aggressive tumor composed of atypical, neoplastic melanocytes. "A crucial role for the CXCL9/10/11-CXCR3 chemokine axis in anti-tumor immunity has been demonstrated in various tumors, and high levels of CXCL9/10 are associated with increased infiltration of immune cells and better prognosis in melanoma patients." (PMID 40867314, 2025). "The observed correlation between GNAS mutations with reduced CXCL9/10/11 expression in human cancers prompted us to examine the effect of GNAS R201C in mouse models of tumor types other than melanoma." (PMID 37714844, 2023). "In melanoma patients, baseline levels of CXCL9, CXCL10, and CXCL11 were associated with response to anti-PD-1 therapy." (PMID 35626062, 2022). "In vitro, melanoma cell lines M537 produced CXCL9 and CXCL10 which was associated CD8+ effector T cells." (PMID 35626062, 2022). "It showed that high levels of CXCL9 were associated with strong infiltration of malignant melanoma by CD8 T cells and improvement in patient survival." (PMID 35530341, 2022). "Authors show here that melanoma-associated lymphatic endothelial cells express G Protein-Coupled Receptor 182 that scavenges CXCL9 and other chemokines necessary for T cell recruitment." (PMID 35013216, 2022). "RT-qPCR assays demonstrated that Ccl2/Ccr2 and Cxcl9/Cxcl10/Cxcr3 levels were higher in B16 melanoma tumors from Cbx3/HP1γ-deficient mice than those from controls." (PMID 34721405, 2021). "In melanoma, elevated tumor levels of T lymphocytes are associated with a better prognosis and elevated expression of CXCL9 and CCL5 has been associated with a better response in metastatic melanoma patients." (PMID 29137331, 2017). "In particular, the chemokine genes CCL4, CCL5 and CXCL9, which were found to be diminished in HS versus LS cases from TCGA, were previously reported to be part of a gene signature associated with enhanced T cell infiltration in melanoma." (PMID 33806316, 2021). "This interferon may then act on tumor DC subsets such as the CD103+ DCs which have been shown to be key producers of CXCL9/10 in a mouse melanoma model and showed an association with CXCL9/10 in human disease." (PMID 30320116, 2018). "Another study illustrated the involvement of CXCL9 in the recruitment of CD8+ T cells to the TME of melanoma mouse model providing effective anti-tumoural response." (PMID 40852716, 2025). "On the other hand, T-cell recruiting chemokines CXCL9, 10, and 11, were highly produced by both macrophages and monocytes, indicating that the myeloid cells infiltrating melanoma can attract T-cells and vice-versa." (PMID 40897819, 2025). "In conclusion, IκBζ expression in melanoma inhibits tumor infiltration of cytotoxic T cells, probably by suppressing the expression of chemokines, such as Ccl5, Cxcl9, and Cxcl10." (PMID 40562773, 2025). "In this study, we show that coadministration of GUA and MAPKi increased melanoma CXCL9/CXCL10 secretion." (PMID 39867570, 2025). "Otherwise, in the case of TNFα and CXCL9, mice with control breast carcinoma tumors exhibited increased levels of these cytokines than melanoma-bearing mice." (PMID 39857957, 2025). "Together this data confirms that constitutive IκBζ expression in melanoma contributes to immunotherapy resistance, supposably by suppressing Ccl5, Cxcl9, and Cxcl10 expression, leading to a continuous exclusion of cytotoxic T cells and NK cells from the TME." (PMID 40562773, 2025). "A higher expression of CCL2, CCL3, CCL4, CXCL9 and CXCL10 transcripts was associated with more CD8+ T cell recruitment into melanoma metastases." (PMID 38928238, 2024). "The response to ICT in melanoma patients correlates to CXCL9/10 expression levels in blood or at the tumor site)." (PMID 39474427, 2024).
melanoma (continued). "Some studies have identified CXCL9 as a T cell chemokine related to the prognosis of head and neck cancer, prostate cancer, melanoma, ovarian cancer, gastric cancer and other tumors, and studies primarily focus on the immune infiltration of CD8 T cells." (PMID 39493752, 2024). "Using the B16-OVA melanoma model, we previously demonstrated that TET2 is important for tumor-associated IFN-γ–regulated expression of chemokines CXCL9, -10, and -11." (PMID 39388288, 2024). "Administration of CXCL10-Fc and CXCL9-Fc limits melanoma growth while selecting subtypes of effector and cytotoxic CD4+ and CD8+ T cells with an IFN-γhigh signature, further limiting tumor growth." (PMID 39474427, 2024). "The high levels CXCL9 and 10 produced by endothelial cells can induce the spontaneous migration of melanoma cells and their subsequent metastasis." (PMID 38928238, 2024). "Specifically, melanoma patients treated with immunotherapy have been shown to have better survival rates when the tumor expresses CXCL9 and/or CXCL10." (PMID 38396726, 2024). "Upregulation of Cxcl9 and Cxcl10 was detected after Mi-2β silencing and anti-PD-1 treatment in melanomas." (PMID 38461299, 2024). "In a clinical trial of melanoma, increased expression of chemokines CXCL9 and CXCL10 after neoadjuvant immunotherapy was highly associated with antitumor efficacy." (PMID 39164491, 2024). "These discoveries were consistent to some extent with the finding that inhibition of CXCL9 expression or protein activity will weaken the therapeutic effect of anti-PD-1/PD-L1 therapy and lead to a dismal prognosis of melanoma patients." (PMID 36845675, 2023). "Deletion of SHP-2 in myeloid cells curbs B16 melanoma growth and boosts tumor concentrations of chemoattractant CXCL9, macrophage-produced IFNγ-induced CXCL9, and CD8+ T cell infiltration into tumors." (PMID 38022587, 2023). "After systematic administration, NPTyr-C9AP with Tyr promoter were demonstrated to induce specific coexpression of CXCL9 and αPD-L1 in multiple melanoma models, while NPSur-C9AP with Sur promoter specifically coexpressed CXCL9 and αPD-L1 in different tumors." (PMID 37031188, 2023). "Taken together, these results reveal that GNAS activation represses Cxcl9/10/11 transcription to impair T cell infiltration and effector functions, thus enabling B16 F10 melanoma to escape immunosurveillance." (PMID 37714844, 2023). "The mice injected with NPTyr-CXCL9 or NPTyr-αPD-L1 that expressed comparable levels of either CXCL9 or αPD-L1 in melanoma were used as controls to evaluate the independent efficacy of CXCL9 or αPD-L1." (PMID 37031188, 2023). "In a mouse study, CD8+ T cell infiltration in HCC was induced by CXCL10 expression, and patients with melanoma who responded to therapy had higher plasma CXCL9 and CXCL10 levels after ICI therapy." (PMID 38133557, 2023). "Taken together, these results demonstrates that the repression of Cxcl9/10 expression by MC1R is critical for B16F10 melanoma to evade immunosurveillance." (PMID 37714844, 2023). "Next, we investigated the efficiency of NPTyr-C9AP for enhancing the recruitment and activation of T cells via melanoma cell-specific expression of CXCL9 and αPD-L1." (PMID 37031188, 2023). "Significantly higher levels of Ifng, Nos2, Il12, Ccl5, Cx3cl1, and Cxcl9 — and, by contrast, significantly lower levels of Arg1 — were detected in the melanomas of Colec11–/– mice, compared with WT mice." (PMID 36883567, 2023). "The forest plot shows that IFNAR2, LBP, CXCL9, and TLR2 are the protective genes for melanoma, while RAC1 and MAPK10 are the risk genes for melanoma." (PMID 37666853, 2023). "The functional relevance of Activin-A signaling in DCs for its tumor-promoting function in melanoma or other cancers, and possible mechanisms of how it attenuates CXCL9/10 secretion in myeloid lineages warrant further investigation." (PMID 38304252, 2023).
melanoma (continued). "Collectively, these results demonstrated the ability of NPTyr-C9AP to specifically express CXCL9 and αPD-L1 in melanoma, laying the foundation for the recruitment and activation of T cells for enhanced antimelanoma immunotherapy." (PMID 37031188, 2023). "Synergistic effects against established subcutaneous melanoma tumours were previously observed with treatment involving intra‐tumoural injection of CXCL10 or CXCL9 combined with IL‐12 treatment and was reported to cure 80% of mice." (PMID 37170733, 2023). "The tyrosinase promoter-driven NPTyr-C9AP can specifically co-express CXCL9 and αPD-L1 in melanoma cells, thereby forming a CXCL9 gradient for T-cell recruitment and high intratumoral αPD-L1 concentration for enhancing T-cell activation." (PMID 37031188, 2023). "In comparison with the negative control PBS or NPControl, NPTyr-CXCL9 or NPTyr-αPD-L1 that expressed CXCL9 or αPD-L1 alone in melanoma significantly inhibited the growth of melanoma, achieving 59.0% or 69.5% tumor growth inhibition rates." (PMID 37031188, 2023). "By integrating a series of bioinformatics methods, our study identified 6 TLR-related genes (IFNAR2, RAC1, LBP, TLR2, MAPK10, CXCL9), which have the potential to serve as new indicators of melanoma progression and prognosis." (PMID 37666853, 2023). "Extending from findings in melanoma, we demonstrate that oncogenic mutations that constitutively activate GNAS repress CXCL9/10/11 expression to dampen antitumor T cell response across human cancer types, including ICB-refractory pancreatic and liver cancers." (PMID 37714844, 2023). "The expression of CXCL9 and αPD-L1 in different melanoma cells, including B16-F10, Clone M-3 and YUMM1.7 cells, were firstly detected after NPTyr-C9AP treatment." (PMID 37031188, 2023). "The efficiency of NPTyr-C9AP for coexpressing CXCL9 and αPD-L1 in melanoma in vivo was first assessed." (PMID 37031188, 2023). "Both DTIC and TMZ have been found to cause melanoma cells to secrete chemokines like CCL5, CXCL9, CXCL10, and CXCL11 in an animal model of melanoma." (PMID 38057843, 2023). "Whereas MC1R activation is restricted to melanoma, GNAS activation by hotspot mutations is observed across diverse cancer types and is associated with reduced CXCL9/10/11 expression." (PMID 37714844, 2023). "This concept has already been confirmed across various entities such as non-small-cell lung cancer or melanoma, in which CXCL9 gene expression emerged, besides TMB, as the strongest predictor of ICB response." (PMID 35314795, 2022). "In human melanoma, CXCL9, expressed by macrophages and DCs10,44, is primarily present in the peritumoral stroma where lymphatic GPR182 locates." (PMID 35013216, 2022). "In contrast with our findings, association between on-treatment variation of serum CXCL9 and response to ICI has been observed in a study of 28 patients with advanced melanoma." (PMID 36007304, 2022). "In the TME of a mouse melanoma model, exogenous supplementation of CXCL9/10 can assist PD-1 antibody in inhibiting tumor growth by increasing the proportion of CXCR3+ T cells." (PMID 36479091, 2022). "Elevated CXCL9 can suppress melanoma growth by regulating effector T cells, thereby promoting anti-tumor adaptive immunity." (PMID 36704353, 2022). "CXCR3 is widely expressed in melanoma cell lines, and CXCL9 stimulation promotes melanoma cell migration." (PMID 36479091, 2022). "It had been found that CXCL9 is expressed in most types of human cancers, such as hepatocellular carcinoma, melanoma, gastric carcinoma, cervical cancer, as well as PDAC." (PMID 34367961, 2021). "Melanoma patients treated with immunotherapy had significantly better survival rates when the tumor expressed CXCL9 or CXCL10." (PMID 34206510, 2021). "Upon stimulation with CXCL9, melanoma transmigration led to the formation of “holes” in the endothelium, caused by the disruption of cell–cell contact." (PMID 34830780, 2021).
melanoma (continued). "CXCL9 and CXCL11 have been associated with activation of Th1 immunity within TME and a favorable response to chemotherapy and immunotherapy in melanoma." (PMID 33968933, 2021). "More specifically, the production of CXCL9 and CXCL10, among other proinflammatory cytokines, has been associated with the severity of melanoma and metastasis." (PMID 34568099, 2021). "Previous studies reported that CXCL9 was correlated with worse OS in renal cell carcinoma, promoted tumor metastasis in melanoma, and enhanced the invasive ability of hepatocellular carcinoma." (PMID 34143198, 2021). "CXCL9 promotes the metastasis of melanoma cells through its combination with CXCR3 to enhance the permeability of tumor blood vessels." (PMID 33767987, 2021). "In humans, the chemokines CCL2, CCL3, CCL4, CCL5, CXCL9, and CXCL10 have been associated with increased T cell infiltrates in melanomas, and the same chemokines were confirmed to attract human CD8+ T cells in vitro." (PMID 34454518, 2021). "Efficient traffic of cytotoxic T lymphocytes (CTLs) to metastatic sites in melanoma patients correlates with the expression of C-X-C Motif Chemokine Ligand 9 (CXCL9) and CXCL10 which are CXCR3 ligands." (PMID 32867162, 2020). "In melanoma, the presence of CXCR3 ligands such as CXCL9, CXCL10, and CXCL11 has been associated with enhanced CD8+ T cell infiltration and hence, better survival prognosis." (PMID 32486450, 2020). "In contrast, it has been reported that the higher CXCL9 levels in melanoma—secreted by the melanoma endothelial cells—disrupt the endothelial barrier, which in turn leads to a higher dissemination of melanoma cells." (PMID 31216755, 2019). "Intralesional BCG can also increase production of CXCL9/10/11 which promotes γδ T cell recruitment and regression of melanomas." (PMID 30320116, 2018). "CXCL9 has been shown to induce chemotaxis in many cells such as melanoma cells, T cells, and HEK293 cells." (PMID 30359318, 2018). "For example, in melanoma, the upregulation of chemokine genes, such as Ccl2, Ccl3, Ccl4, Ccl5, Cxcl9, and Cxcl10, in the tumor microenvironment correlates with the influx of activated T cells into the tumor supporting the antitumor immune response." (PMID 29410666, 2018). "Expression of CXCR3 on circulating T cells or its chemokine ligands, CXCL9 and CXCL10, in tumor tissues has been reported to be associated with elevated intratumoral T cell infiltration in melanoma and colorectal cancer patients." (PMID 28407741, 2017). "Most chemokines were expressed intracellularly in all melanoma cell lines (CXCL9, CXCL11, CXCL12, CCL19, CCL21 and CCL27)." (PMID 24559071, 2014). "Low concentrations of the chemokine CXCL9 have a chemoattractive effect, whereas high concentrations have a repulsive effect on the melanoma cells." (PMID 21179030, 2011). "Addition of anti-CXCL9 or anti-CXCR3 antibodies to the co-cultures delayed the TEM of melanoma cells." (PMID 21179030, 2011). "When cells were preincubated with soluble CXCL9, melanoma cell infiltration led to increased hole formation and to complete monolayer disruption." (PMID 21179030, 2011). "As expected from the TEM assays, the addition of soluble CXCL9 significantly accelerated melanoma-mediated breakdown of the EC monolayer in a concentration-dependent manner." (PMID 21179030, 2011). "CXCR3 expression in human and murine melanoma cell lines has been suggested by others to mediate directional cell migration along the chemokine gradients of CXCL9, CXCL10 and CXCL11." (PMID 21179030, 2011). "To study the influence of CXCL9 expression on endothelial barrier function during melanoma cell attachment and infiltration, we used the ECIS technology." (PMID 21179030, 2011). "To further confirm that TuECs express high levels of CXCR3 ligands, we isolated LECs and blood endothelial cells (BECs) from normal human skin and TuECs from melanoma metastases and compared the expression levels of CXCL9 and CXCL10 using RT–PCR." (PMID 21179030, 2011).